RHOBTB2 (Rho related BTB domain containing 2)
Description:
Regulator of cell proliferation and apoptosis. It likely functions as a substrate-adapter that recruits key substrates, e.g. MSI2, to CUL3-based ubiquitin ligase complexes for degradation. Required for MSI2 ubiquitination and degradation.
Synonyms: DBC2; KIAA0717; DEE64; EIEE64; p83
Tractability: Antibody: its Gene Ontology location is reachable by antibodies, with medium confidence; the Human Protein Atlas places it where antibodies can reach. PROTAC: UniProt records ubiquitination sites on it; ubiquitination databases record sites on it.
Gene: Protein-coding gene on chromosome 8 (22,987,222 to 23,020,723, forward strand). Ensembl gene ENSG00000008853.
Subcellular location (Human Protein Atlas): Plasma membrane
Pathways (Reactome):
Signal Transduction: RHOBTB2 GTPase cycle
Gene Ontology:
Molecular function: protein binding; ubiquitin-like ligase-substrate adaptor activity; G protein activity; GTP binding; GTPase activity
Biological process: protein ubiquitination; ubiquitin-dependent protein catabolic process; actin filament organization; establishment or maintenance of cell polarity; regulation of cell shape; small GTPase-mediated signal transduction
Cellular component: Cul3-RING ubiquitin ligase complex; cytoplasmic vesicle; cytoskeleton; endosome membrane
Genetic constraint (gnomAD): Loss-of-function variants: 35 observed, 61 expected, observed/expected ratio (o/e) 0.57, 90% interval 0.44 to 0.76. The upper end of that interval is the gene's LOEUF score, 0.76, which puts it in group 3 of 6, group 1 being the genes least tolerant of losing a copy. Missense variants: 745 observed, 1,019.3 expected, observed/expected ratio (o/e) 0.73, 90% interval 0.69 to 0.78. Synonymous variants: 388 observed, 406.55 expected, observed/expected ratio (o/e) 0.95, 90% interval 0.88 to 1.04.
Gene-disease validity (ClinGen):
ClinGen rates the evidence that RHOBTB2 causes each of these diseases.
complex neurodevelopmental disorder (autosomal dominant; autosomal recessive): Definitive. A disorder that involves more than one phenotype associated with the central nervous system, including but not limited to intellectual disability, autism, and seizures (epilepsy).
Homologues: Orthologues: chimpanzee RHOBTB2 (99% identical), macaque RHOBTB2 (99% identical), dog RHOBTB2 (99% identical), guinea pig RHOBTB2 (99% identical), pig RHOBTB2 (99% identical), mouse Rhobtb2 (98% identical), rat Rhobtb2 (98% identical), rabbit RHOBTB2 (97% identical), zebrafish rhobtb2b (75% identical), tropical clawed frog rhobtb2 (74% identical), zebrafish rhobtb2a (54% identical). Paralogues in human: RHOBTB1 (67% identical), RAC1 (13% identical), RHOT1 (13% identical), RAC3 (12% identical), CDC42 (12% identical), RHOQ (12% identical), RAC2 (12% identical), RHOG (12% identical), RHOT2 (12% identical), RHOJ (11% identical), RHOU (11% identical), RHOA (11% identical), and 10 more.